EPCAM (epithelial cell adhesion molecule)
Diseases named in the same sentence as EPCAM in open-access papers (continued):
Sharing a sentence is not in itself a finding about the gene and the disease.
tumor (continued). "As it is frequently highly expressed in tumor tissues and metastatic cancer cells in transit via blood or lymphatic vessels, EpCAM has gained attention as a potential target for diagnostic and antibody-based immunotherapies for a spectrum of malignancies." (PMID 26317650, 2015). "There is evidence that tumor-promoting EpCAM activities are modulated by the association with claudin-7." (PMID 25514462, 2015). "Our data demonstrate that the adoptive transfer of human PBLs with CARs specific for EpCAM can cause PC3M tumor cell killing in vitro and in vivo." (PMID 25636521, 2015). "Dynamic changes observed in EpCAM expression have been linked to a changing tumor cell microenvironment during cancer progression." (PMID 26317650, 2015). "The integrity and size of CS tumor spheroids, found in ex vivo cultures containing tumor cells expressing EpCAM and autologous tumor associated lymphocytes, were diminished after exposure to solitomab." (PMID 26474755, 2015). "EpCAM is a tumor-associated membrane marker overexpressed in various epithelial malignancies and it has been reported to enhance tumor signaling and proliferation." (PMID 25947366, 2015). "Tumor cells were highly susceptible to T cell mediated killing if EpCAM was present while negligible cytotoxicity was seen in cell lines with low level of EpCAM expression." (PMID 26474755, 2015). "Other cell adhesion proteins such as EpCAM have been implicated in the budding process, with loss of membranous expression identified in tumor buds." (PMID 25806371, 2015). "Overexpression of EPCAM is associated with high proliferation and invasive activity in tumor cells as well as with poorer survival in cancer patients." (PMID 24718422, 2014). "Previous studies have showed that overexpression of EPCAM is significantly associated with the poor clinical outcome of HCC, and EPCAM-positive cancer patients commonly exhibit an advanced tumor stage." (PMID 24718422, 2014). "PIK3CA mutation analysis was then performed on the 242 EpCAM-captured single tumor cells (185 CTCs, 24 DTCs, and 33 tumor cells)." (PMID 24947048, 2014). "The mechanism of action of this molecule is pleiotropic, and EpCAM has been described as a highly immunogenic tumor-associated antigen." (PMID 23959111, 2014). "We selected two microRNA families, miR-181(miR-181b, miR-181c and miR-181d) and miR-130 (miR-130a and miR-130b) families based on their previous association with EpCAM and literature reports of cancer to find out their role in RB tumor cell proliferation." (PMID 25502397, 2014). "Additional transmembrane proteins such as CD44 and EpCAM have been associated with tumour-initiating frequency and are abundantly expressed in TICs of numerous tumour entities." (PMID 23150174, 2013). "In summary, we present a comprehensive overview of cleavage processes associated with the tumour and stem cell associated receptor EpCAM at the single amino acid level." (PMID 24009667, 2013). "In another aspect, the loss of EpCAM has been advocated to promote tumor progression through weakening cell-cell adhesion." (PMID 22482828, 2012). "Previous studies have implicated that epithelial cell adhesion molecule (EpCAM) is an biomarker of HCC tumor-initiating cells with stem/progenitor cell features and EpCAM+ HCC cells were correlated with tumor progression and invasiveness." (PMID 22962603, 2012). "The results demonstrate that EpCAM and CD133 positive cells were higher in the post-TACE tumors and higher pretransplant EpCAM immunostaining significantly correlated with the risk of 2-year tumor recurrence." (PMID 23216644, 2012). "EpCAM mediates epithelium-specific, Ca2+-independent homotypic cell-cell adhesion and represents the first human tumor associated antigen to be discovered." (PMID 22482828, 2012).
tumor (continued). "The mode of action and the efficacy of trifunctional bispecific antibodies (trAb) binding with high affinity to targeted tumor-associated surface proteins like EpCAM or HER2/neu are well described." (PMID 23134699, 2012). "Univariate analysis showed that high EpCAM status was significantly associated with more undifferentiated tumor histology and having undergone TACE." (PMID 23216644, 2012). "Other tumor-associated antigens, such as the adhesion molecule EpCAM, the epithelial mucins CA125 and MUC1, and the Folate Receptor as well as molecules expressed by immune cells such as CD3 and CTLA-4 are under evaluation." (PMID 22235224, 2011). "The largest effect is nearly 300-fold higher expression of epithelial cell adhesion molecule (Epcam), a tumour-associated protein." (PMID 22073188, 2011). "This decline in membranous EpCAM expression at the tumour front was associated with nuclear β-catenin localization, which is associated with reduced cell–cell adhesion and increased migratory potential." (PMID 21339979, 2010). "Epithelial cell adhesion molecule EpCAM (CD326; 17-1A antigen) was among the first human tumor-associated antigens discovered." (PMID 21044305, 2010). "The aberrant expression of the transmembrane protein EpCAM is associated with tumor progression, affecting different cellular processes such as cell–cell adhesion, migration, proliferation, differentiation, signaling, and invasion." (PMID 19609345, 2009). "As TACSTD1 encodes EpCAM, the target antigen for the BerEP4 antibody, it was expected that all captured tumour cells would express this gene." (PMID 19500345, 2009). "Epithelial cell adhesion molecule is one of the first tumour-associated antigens identified with monoclonal antibodies." (PMID 19002182, 2008). "Recently, the gene for EpCAM was renamed from GA733-2 to TACSTD1, the abbreviation for ‘tumour-associated calcium signal transducer protein 1-precursor’." (PMID 17211480, 2007). "In his introductory remarks, G Riethmueller (Munich, Germany) pointed out that the first human tumour-associated antigen identified with monoclonal antibodies (mAb) was in fact EpCAM or 17-1A antigen." (PMID 17211480, 2007). "A significant association was found between EpCAM overexpression and histological grade (p = 0.008), with moderately and poorly differentiated tumours demonstrating higher odds of overexpression compared to well-differentiated tumours (OR = 12.25; 95% CI: 2.18-68.6)." (PMID 42164196, 2026). "Corresponding mProtein expression was assessed using fluorescence‐labeled DLL3 antibody in DLL3/epithelial cell adhesion molecule (EpCAM)/receptor tyrosine kinase‐like orphan receptor 1 (ROR1)+ tumor‐associated EVs (tEV), captured with a mixture of DLL3, EpCAM, and ROR1 monoclonal antibodies." (PMID 40285610, 2025). "Relying on EpCAM alone would risk missing a clinically significant subset of tumor cells." (PMID 40671945, 2025). "Consequently, investigating the role of EpCAM and its associated secreted proteins within the tumor microenvironment is of considerable interest." (PMID 40316530, 2025). "While its expression in TNBC is variable, EpCAM overexpression is associated with poor prognosis and may indicate an aggressive tumor phenotype, suggesting its potential as a target for specific therapeutic approaches." (PMID 40806559, 2025). "EpCAM-positive Liver-CSCs—whether detected as circulating tumor cells (CTCs) or within the TME—consistently associate with unfavorable prognosis, including reduced recurrence-free survival (RFS) and overall survival (OS) after curative resection." (PMID 41438763, 2025). "EpCAM was one of the first tumor-associated antigens to be described." (PMID 40358156, 2025).
tumor (continued). "Compared to the original tumor, PDX257S exhibited a significant three‐fold increase in mutational burden, involving more oncogenic drivers, along with elevated expression of EpCAM, a recognized marker for cancer stemness associated with a more aggressive subtype of BC tumor." (PMID 40801146, 2025). "This immunosuppressive TME poses challenges for effective cancer therapies, including the use of chimeric antigen receptor (CAR) T cells to significantly inhibit tumor growth and improve survival by targeting tumor-associated antigens like EpCAM, EGFR, and ROR1." (PMID 41375062, 2025). "Furthermore, AnnexinV+EpCAM+ASGPR1+ tumor-associated microparticles (taMPs) were significantly elevated in the serum of CCA patients and demonstrated diagnostic capability with both sensitivity and specificity exceeding 78%." (PMID 41487574, 2025). "Interestingly, EpCAM expression declined in advanced-stage disease, suggesting a potential role in earlier tumor development or loss of epithelial characteristics during tumor progression." (PMID 40806559, 2025). "The EpCAM gene encodes a type‐I transmembrane glycoprotein that is found in elevated levels within various malignant epithelial cells and facilitates tumor proliferation by affecting the expression of several oncogenes, such as Cellular Myelocytomatosis (c‐myc) and additional cyclins." (PMID 40391083, 2025). "However, in cancer, EpCAM overexpression is associated with increased proliferation, migration, invasion, and tumor metastasis." (PMID 40236691, 2025). "Therefore, we selected this antibody combination for isolating DLL3/EpCAM/ROR1+ tumor‐associated EVs (tEV), as it provides superior performance across human samples." (PMID 40285610, 2025). "The AdnaTest workflow includes two steps: AdnaSelect enables the immunomagnetic enrichment of CTCs from peripheral blood using magnetic beads conjugated to antibodies against epithelial (such as epithelial cell adhesion molecule [EpCAM]) and tumor-associated antigens on the cell surface." (PMID 38627648, 2024). "Although numerous antigens have been identified as potential targets (e.g., Trop2, GD2, ROR1, MUC1, EpCAM), the ideal target should represent the most relevant obstacle, thereby minimizing on-target/off-tumor toxicities and reducing tumor escape via antigen loss and intrinsic heterogeneity." (PMID 39062758, 2024). "Furthermore, EpCAM exhibited a notable correlation with the tumor mutational burden across a wide range of cancer types, including KIRC." (PMID 38187284, 2024). "Moreover, we analysed the expression levels of key markers associated with increased tumour aggressiveness and metastatic potential, such as EPCAM." (PMID 38926706, 2024). "Furthermore, the expression of EpCAM in tumor cells is recognized to be linked with the presence of stemness." (PMID 39456890, 2024). "The evaluation of EpCAM expression in the context of clinicopathological and molecular features demonstrated that—depending on the tumor type—both upregulation and reduced expression of EpCAM can be associated with unfavorable tumor features and tumor progression." (PMID 38786342, 2024). "EpCAM overexpression is considered an early indicator of certain malignant tumors or precancerous lesions and associated with tumor size and lymph node metastasis in patients with GC." (PMID 38952968, 2024). "Since its discovery, EpCAM has come to be associated with a plethora of roles, including cell adhesion, modulating other adhesion molecules, intracellular signalling, stemness in circulating tumour cells and as a drug target." (PMID 37533952, 2023). "Additionally, the overexpression of AREG and EPCAM is associated with tumor progression and unfavorable survival outcomes in multiple cancer types." (PMID 36341526, 2023). "The tumor cells frequently express adenocarcinoma-associated markers, such as EpCAM, CK7, and CK19." (PMID 37761023, 2023).
tumor (continued). "The degradation of these complexes may result in the re-expression of some silenced genes, such as epithelial cell adhesion molecule (EpCAM), which may be associated with tumor development." (PMID 37127643, 2023). "Also, tumours overexpressing EpCAM had significant association with tumour-associated lymphocytes (p < 0.02 each)." (PMID 37533952, 2023). "Also, EpCAM overexpression was significantly associated with reduced E-cadherin (p < 0.035) expression in tumour cells." (PMID 37533952, 2023). "As a diagnostic marker, EpCAM has found utility in detecting mature carcinoma cells in mesenchymal organs like blood, bone marrow, or LNs, and particularly in assessing rare circulating tumor cells in carcinoma patients." (PMID 38152574, 2023). "This approach includes positive selection with antibodies against tumor-associated antigens such as EpCAM, CKs, mucin-1, human epidermal growth factor receptor 2, or epithelial growth factor receptor and negative selection with antibodies against the common leukocyte antigen CD45." (PMID 36627698, 2023). "Obviously, the cadherin binding related genes including CTNNB1, CDH1, ITGA6, KRT18, and PROM1 were significantly associated with EpCAM, which also implied that EpCAM could play a role in tumor metastasis." (PMID 35517503, 2022). "In return, EpCAM as a human TAA can cause tumor immune evasion via Th2 responses’ development." (PMID 35986321, 2022). "Furthermore, CSC markers OCT4, CD133, and EpCAM were positively associated with tumor grading, staging and metastasis and/or survival in GBC patients." (PMID 35163489, 2022). "Cancer development frequently involves a transition of cells from an epithelial phenotype to a mesenchymal phenotype (a process referred to as epithelial-to-mesenchymal transition, or EMT), which results in the downregulation of EpCAM expression and is associated with tumor-initiating potential." (PMID 36358657, 2022). "In addition to its role in normal epithelial tissues, EpCAM plays an important role in tumor development, and was the first identified human tumor-associated antigen." (PMID 35735360, 2022). "Moreover, tumor-associated macrophages (TAMs) impede EpCAM expression probably through TGFβ-induced EMT signaling." (PMID 36077658, 2022). "Thus, quantifications and comparisons of GD2 levels between high- and low-risk groups after sorting EPCAM + tumor cells are expected." (PMID 35493068, 2022). "Moreover, EpCAM expression is associated with cells that exhibit tumour‐initiating capabilities and tumorigenesis." (PMID 35152538, 2022). "It has been only in the last few years that other immunotherapies have regained interest, not just against PSMA but also anti-PSA, anti-PAP, anti-PSCA, or other more general tumor associated antigens such as B7-H3 or Epithelial Cell Adhesion Molecule (EpCAM) precursor." (PMID 35327339, 2022). "Hence, these miRNA families are associated with cancer stem cells in EpCAM+ tumors, and their inhibition reduces tumor cell proliferation." (PMID 35986321, 2022). "The limitation of the fact that CellSearch® detects EpCAM+ cells leading to the loss of EpCAM-cells has been improved in other methods by combining different specific tumor markers, including EGFR, cytokeratin, HER2, folic acid receptors (FRs), and recombinant VAR2CSA (rVAR2)." (PMID 35962400, 2022). "Because of this, a minor set of five additional markers (CD99, GD2, CD271, EpCAM, and numyogenin) was selected from all tumor-associated proteins investigated, for the differential diagnosis between the four major subgroups of extracranial SRCT vs. other pediatric tumors." (PMID 34638431, 2021).
tumor (continued). "EpCAM mutations could potentially serve as a biomarker of increased CTSL activity in the tumor microenvironment and identify patients that would benefit from protease inhibitors targeting CTSL." (PMID 33980181, 2021). "Moreover, 37 ± 6% of EpCAM+E-cadherin+ tumour cells expressed αV in association with β6, while only 14% ± 4% of non-epithelial αV+EpCAMnegE-cadherinneg cells were β6+, suggesting that αV pairs with β8 or β3 in αV+β6neg cells." (PMID 34471106, 2021). "EpCAM expression was identified as the major characteristic of retained epithelial differentiation of carcinoma cells, and loss of EpCAM expression at the edges of tumor areas was frequently accompanied by expression of the mesenchymal marker vimentin." (PMID 34693227, 2021). "Interestingly, despite the low expression level of EpCAM on PC3 cells, lymphocytes targeting EpCAM can cause significant tumour‐killing effects and inhibit the metastasis of PC3 cells in NOD/SCID mice." (PMID 34585512, 2021). "Our study demonstrates a molecular mechanism of tumor progression in EpCAM mutated tumor cells." (PMID 33980181, 2021). "In addition to its role in healthy tissues, EpCAM plays a prominent role in cancer biology and was the first human tumor-associated antigen to be identified using monoclonal antibodies." (PMID 34209658, 2021). "Additionally, EpCAM can be detected in the bodily fluid of cancer patients suggesting that EpCAM is a pathophysiologically relevant anti-tumour target as well as being utilized as a diagnostic/prognostic agent for a variety of cancers." (PMID 32046162, 2020). "In addition, saturation of EpCAM by co-injecting a large excess of unlabeled Ec1 resulted in a significant (p < 0.01, unpaired t-test) reduction in tumor uptake of both variants." (PMID 33066684, 2020). "While EpCAM expression on most carcinoma is a highly attractive feature for tumor-associated antigens, expression on healthy epithelia—mostly of the gastrointestinal tract—will limit the therapeutic window of EpCAM-targeted therapies and call for potential side effects." (PMID 32507912, 2020). "EpCAM overexpression is usually associated with tumor progression, especially metastasis." (PMID 32039729, 2020). "High expression of EpCAM can promote sustained proliferation and tumor/metastatic growth and might thereby be associated with poor prognosis." (PMID 32507912, 2020). "The activation of EMT allows for the regulation of several molecules including E-cadherin and EpCAM in tumor cells and causes these cells to lose cell junctions, gain mesenchymal properties, followed by dissociation from the original tumor mass and the initiation of metastasis cascade." (PMID 32599893, 2020). "Here, we addressed the issue by proposing a combinatorial approach targeting two different tumor-associated antigens (EpCAM and EGFR) with a bivalent bispecific antibody and multivalent costimulatory antibody-fusion proteins with affinities in the lower nanomolar range, respectively." (PMID 32504247, 2020). "This suggests that EpCAM overexpression in tumor cells might be associated with the presence of a higher number of cancer stem cells (CSCs) that can become metastatic-initiator cells (MICs)." (PMID 32764280, 2020). "In addition, available diagnostic tumor samples (n = 12) before start of NACT from patients in the interval cytoreductive surgery group were immunohistochemically stained for EpCAM, αvβ6 and FRα." (PMID 32545676, 2020). "Interestingly, association of EpCAM, E Cadherin and integrin αvβ6 on tumor cells can also play additional role and trigger tumor-mediated fibroblast activation, thereby influencing both gene expression and tumor response to therapeutic agents." (PMID 31225512, 2019). "EpCAM is identified as a CSC marker that is closely linked to tumor progression." (PMID 31324239, 2019). "EPCAM is a carcinoma-associated antigen which often highly expresses in tumor cells." (PMID 30867030, 2019).